RC3H1-DT (RC3H1 divergent transcript)
Synonyms: LINC02776
Gene: Long non-coding RNA gene on chromosome 1 (174,021,681 to 174,023,628, forward strand). Ensembl gene ENSG00000224977.
Diseases named in the same sentence as RC3H1-DT in open-access papers:
RC3H1-DT is named in the same sentence as 2 diseases in open-access papers, as found by Europe PMC text mining. Sharing a sentence is not in itself a finding about the gene and the disease.
RC3H1-DT shares sentences with these, for which no sentence is quoted: ovarian carcinoma (1 paper); Tumour (1).